IL31 (interleukin 31)
Diseases named in the same sentence as IL31 in open-access papers (continued):
Sharing a sentence is not in itself a finding about the gene and the disease.
Pruritus (continued). "Pruritus can be stimulated by eosinophils as they release toxic granule proteins, neuromediators, and cytokines, in particular IL-31." (PMID 34097126, 2021). "These MrgprC11+ sensory nerve fibers mostly coexpress IL-31 receptor (IL-31RA/OSMRβ), which signals IL-31-induced pruritus to DRG neurons, the spinal cord, the hypothalamic tract and finally to the brain." (PMID 33924978, 2021). "The IL-31-induced pruritus is mediated by NKB and its receptor NK3R, and then by GRP and its receptor GRPR." (PMID 33924978, 2021). "Serum levels of IL-31 are elevated in canine atopic dermatitis and are significantly correlated with the pruritus score of afflicted dogs." (PMID 33924978, 2021). "In this regard, IL-31 has been shown to correlate with disease severity and pruritus in AD patients." (PMID 33681256, 2021). "The evidence above supports the critical role of IL-31 in both pruritus and skin hypersensitivity, which are characteristic of AD." (PMID 34281281, 2021). "Patients with higher serum IL-31 levels at screening tended to have greater pruritus VAS reductions following nemolizumab treatment." (PMID 33754202, 2021). "Cytokines that are important for pruritus in AD (e.g., IL-31, IL-4, IL-13, and TSLP) transmit their signals via JAK-1 and JAK-2 into the cells." (PMID 34026782, 2021). "Most patients (around 88%) with CTCL are affected by pruritus, and studies have demonstrated elevated levels of IL-31, IL-31RA, and OSMRβ within the epidermis of affected patients, as well as increased serum IL-31 levels." (PMID 33644103, 2021). "Similar findings were confirmed in mice, where elevated IL-31 levels lead to pruritus, alopecia, and skin lesions." (PMID 32664385, 2020). "Altogether, there is strong evidence that IL-31 induces pruritus and plays a crucial role in autoimmune skin diseases." (PMID 32664385, 2020). "IL-31 is a known endogenous pruritogen that plays an important role in pruritus development by promoting the release of inflammatory cytokines and the growth of the sensory nerve." (PMID 32454868, 2020). "It has been reported that transgenic mice overexpressing IL-31 develop AD-like skin lesions with severe pruritus." (PMID 31434203, 2019). "In a canine IL-31 pruritus model, anti-pruritic activity of this drug was greater than that of both prednisolone and dexamethasone." (PMID 31068210, 2019). "IL-31 has thus far been shown to play a prominent role in common inflammatory skin diseases, such as atopic dermatitis, particularly in relation to pruritus." (PMID 31281316, 2019). "Because BP patients experience pruritus particularly in lesional skin the increases in IL-31 levels in blister fluids offer a plausible explanation for this localized itch." (PMID 31281316, 2019). "Although IL-31/IL-31RA interaction has been identified as one of the key determinants of pruritus in AD, there are limited reports regarding the effect of IL-31/IL-31RA interaction on Th2-deviated immune conditions in AD." (PMID 31434203, 2019). "Oclacitinib is a Janus kinase (JAK) 1 enzyme inhibitor and blocks JAK1-dependent cytokines, such as IL-2, IL-4, IL-6, IL-13, and IL-31 involved in allergy, inflammation, and pruritus." (PMID 31068210, 2019). "IL-31, considered to be responsible for the development of pruritus in AD, was one of the first therapeutic targets." (PMID 29713240, 2018). "Interleukin-31 (IL-31) is a recently identified cytokine produced by Th2 cells that is involved in the development of atopic dermatitis-induced skin inflammation and pruritus." (PMID 28428802, 2017). "The important role of IL-31 in atopic dermatitis, in particular its impact on intensity of pruritus, is well known." (PMID 29259273, 2017). "Thus, EPAS1 may be a therapeutic target for controlling IL-31-associated itch." (PMID 28067314, 2017). "IL-31 monoclonal antibody provides an approximately 60% reduction in pruritus according to owners and up to 50% decrease of CADESI in most atopic patients." (PMID 29056696, 2017).
Pruritus (continued). "The haplotype AAA or GAA of IL-31 was correlated with increased serum levels of IL-31 and severe pruritus in certain populations." (PMID 27483258, 2016). "Although the role of distinct players in AD is ambiguous, IL-31 strongly contributes to pruritus in AD also correlating with the severity of the disease." (PMID 27294147, 2016). "IL-31 has been suggested to be a major factor inducing pruritus in AD, since both IL-31 and its receptor are overexpressed in lesional skin." (PMID 27043528, 2016). "The link between pruritus and IL-31 has also been confirmed by a study showing that transgenic mice models over-expressing IL-31 developed severe pruritus and an increase in mast cells." (PMID 26316486, 2015). "Together with previous reports on the participation of IL-31 in pruritus and dermatitis in animal models and IL-33 in AD, our results provide insight of the pathological roles of IL-31 and IL-33 in the pathogenesis of AD." (PMID 22272250, 2012). "In addition, IL-31-displaying VLPs suppress the development of IL-31-induced pruritus, confirming in vivo target neutralisation." (PMID 41746052, 2026). "Possible causes of sudden loss of efficacy during long-term treatment may also include the presence of pruritus-mediating cytokines other than IL-31." (PMID 41303472, 2025). "Therefore, IL-31 is considered a key factor in both pruritus induction and the formation of nodules in PN." (PMID 40104458, 2025). "This induces IL-31-mediated pruritus and drives IL-17/IL-22-dependent chronic inflammation." (PMID 40771817, 2025). "IL-31 directly induces pruritus, while IL-4 and IL-13 enhance itching." (PMID 40109398, 2025). "IL-31 is particularly important in the pathogenesis of pruritus in dogs." (PMID 41303472, 2025). "Similarly, we investigated the effects of histamine and IL-31, both of which are chemical mediators that induce pruritus." (PMID 40677708, 2025). "DHS was shown to suppress pruritus-related cytokines IL-31 and IL-6 in LPS-treated microglia." (PMID 40443235, 2025). "In addition, IL-31—secreted by Th2 cells—plays a key role in mediating the pruritus observed in early ACE by directly stimulating cutaneous sensory neurons." (PMID 41226755, 2025). "Although little research has been done on IL-31 production in CNS, IL-31 receptors (IL-31RA and OSMR β) have been extensively found in the brain tissues and spinal cord and IL-31 is acknowledged as causing pruritus in AD." (PMID 40443235, 2025). "IL-31, predominantly secreted by Th2 cells, is a principal mediator of pruritus in PN." (PMID 41226755, 2025). "M2 macrophages express IL-31 and may be responsible for pruritus in several dermatoses, such as stasis dermatitis and scabies." (PMID 38493053, 2024). "Furthermore, transgenic mice overexpressing IL-31 developed severe pruritus and skin lesions, suggesting a role for IL-31 in allergic dermatitis." (PMID 38590314, 2024). "Additionally, a single dose of IL-31 in mice induced strong pruritus upon skin and intrathecal injection, with concentrations significantly increased in the skin of mice with atopic-like dermatitis, leading to persistent scratching behavior." (PMID 38590314, 2024). "Research conducted in animal models suggests that IL-31 may play a critical part in the pruritus pathomechanism." (PMID 39064040, 2024). "An increase in skin IL-31 may be associated with pruritus in diabetes mellitus (DM), and ongoing clinical trials aim to evaluate the systemic treatment effects on IL-31 and pruritus in DM." (PMID 38590314, 2024). "Dupilumab may also impact the activity of IL-31, an important driver of pruritus, as IL-4 stimulation upregulates IL-31 receptor A expression and is the central driver of T helper 1 or 2 cell precursor polarization." (PMID 39006917, 2024).
Pruritus (continued). "Therapeutic blocking of the IL-4 and IL-13 receptors with dupilumab in CTCL is thought to reduce the synthesis of IL-31, the neuroimmune ‘‘itch cytokine’’, alleviating cancer-related pruritus by directly affecting neurons, even in cases unrelated to Th2 cell inflammation." (PMID 38398754, 2024). "However, the extent of the correlation between IL-31 and pruritus is still debated in this setting and a broader role of this cytokine in the pathogenesis of CTCL has been inconsistently confirmed in the current literature." (PMID 38398754, 2024). "Piperine could also reduce secretion of IL-31, suggesting that it has alleviating effect on pruritus." (PMID 38535499, 2024). "Finally, it will be intriguing to evaluate the efficacy of nemolizumab, a monoclonal antibody targeting IL-31, on disease activity and pruritus of BP." (PMID 36814775, 2023). "By blocking IL-4 and IL-13 on sensory neurons and inhibiting IL-31 production, it may decrease pruritus in PLCA patients as well." (PMID 38137741, 2023). "Subsequently, this intravenous IL-31 canine pruritus model was used to determine the onset and duration of action of the current commonly used treatments for canine AD such as oclacitinib (Apoquel, Zoetis; Kalamazoo, MI, USA), lokivetmab (Cytopoint, Zoetis) and glucocorticoids." (PMID 37235412, 2023). "Blocking IL-31RA may reduce the IL-31 cascade, therefore modulating the inflammation and pruritus in AD." (PMID 36839897, 2023). "IL-31 is involved in inflammation, impaired barrier function, and pruritus." (PMID 37834183, 2023). "Given that the number of dermal mDCs increased with itch severity, we further hypothesized that mDCs may additionally be a key producer of IL‐31." (PMID 36789100, 2023). "Considering the connection between IL-31 in the pathogenesis of AD and pruritus, a therapeutic approach targeting the IL-31 axis may expand the scope of AD treatment." (PMID 36839897, 2023). "We speculate that OSM may suppress IL-31-induced pruritus by reducing IL31RA expression and downstream ERK activity in both DRGs and keratinocytes." (PMID 38035099, 2023). "Additionally, interleukin-31 (IL-31), which is produced by various immune cells including T helper 2 (Th2) cells, mast cells, macrophages, and dendritic cells, has some importance in pruritus and inflammatory responses." (PMID 37762898, 2023). "Furthermore, in patients with allergic contact dermatitis, serum levels of IL-31 are significantly higher as compared to healthy controls and correlate with the severity of pruritus." (PMID 37555911, 2023). "IL-4, IL-5, and IL-31 cytokines are relevant for pruritus and could be targets for therapeutic interventions." (PMID 37874473, 2023). "These correlations, as detailed in the results section and elaborated upon in the subsequent paragraphs of this discussion, underscore the connections we identified between serum IL-31 levels and the specific clinical impacts of pruritus, assessed through the presented scoring systems." (PMID 37762898, 2023). "The oral JAK1 inhibitor upadacitinib might suppress the effects of IL-31 or IL-4/IL-13 and block the communication between nerves and eosinophils, leading to the suppression of pruritus." (PMID 36983203, 2023). "At the same time, IL-31 can promote the occurrence of cardiovascular diseases, participates in a variety of hematological malignancies and the occurrence of pruritus, and is positively correlated with the level of pruritus." (PMID 36769725, 2023). "In atopic dermatitis, IL-31 is mainly known to induce pruritus through neuro-immune interaction." (PMID 38132113, 2023). "Indeed, IL-31 not only correlates with pruritus in inflammatory skin diseases, such as atopic dermatitis and urticaria, there is also a trend between pruritus severity and IL-31 expression in the skin of patients with BP." (PMID 36979421, 2023). "Pruritus develops due to interactions between the immune and nervous systems attributed to IL-31." (PMID 37570323, 2023).
Pruritus (continued). "Further, IL-31-induced pruritus may trigger itch–scratch cycle, which can damage the stratum corneum and lipid distribution." (PMID 38132113, 2023). "Additionally, IL‐31R is expressed on sensory neuron endings; thus IL‐31 also induces pruritus through direct stimulation." (PMID 36477831, 2023). "Moreover, cASCs or cASC-EVs reduced IL-31/TRPA1-mediated pruritus and activation of JAK/STAT signaling pathway." (PMID 35563259, 2022). "Oclacitinib inhibits pathways involved in many pro-inflammatory, pro-allergic, and pruritic cytokines implicated in atopic dermatitis including interleukins (IL) 2, 4, 6, and 13 and is also involved in signaling IL-31, which has been shown to play a key role in canine pruritus." (PMID 36256616, 2022). "The role that IL-31 plays, both in sunburns and AD-manifestation development and pruritus, suggests a common ground where UVB rays may play both a protective and pejorative effect." (PMID 35742951, 2022). "Accordingly, targeting IL-31 is a potential therapy for DM-related pruritus." (PMID 35885674, 2022). "Transient receptor potential A1 (TRPA1) is mainly involved in non-histamine such as Il-31, Tslp-related pruritus, which is associated with pruritic transmission in the central nervous system." (PMID 36051905, 2022). "Furthermore, cASCs and cASC-EVs ameliorated pruritus by reducing IL-31/TRPA1 through the inhibition of JAK-STATs signaling activation." (PMID 35563259, 2022). "A major function of IL-31 in AD is the induction of pruritus in the skin." (PMID 35742951, 2022). "Other itch mediators such as IL-6, IL-33, and IL-31 may be involved in the mechanism of CLE-related pruritus." (PMID 35885674, 2022). "Interestingly, due to its involvement in pruritus development, IL-31 has recently been shown to be a therapeutic target in treatment of IBH." (PMID 35913947, 2022). "Future studies should focus on the role of IL-31 and its inhibition for the control of pruritus." (PMID 35558086, 2022). "Thus, IL-31 can be a suitable target for the treatment of pruritus as a preliminary study in insect allergic horses has shown." (PMID 34357916, 2021). "The aim of the current study was to investigate translational IL31 levels in serum and cutaneous IL31 transcriptional expression in pruritic and non-pruritic CTCL variants and to study the relation of IL31 with regard to pruritus and clinical disease stage." (PMID 34027133, 2021). "However, previous studies focusing on IL31 in CTCL patients have reported variable results regarding the correlation between IL31 levels and pruritus intensity, disease severity or both parameters." (PMID 34027133, 2021). "Although there are some inaccuracies in the literature, this observation might be proof that IL-31 contributes to the induction of pruritus in psoriasis." (PMID 33467067, 2021). "In addition, the administration of IL-31 intravenously, intradermally, subcutaneously or intrathecally induces severe pruritus in normal mice." (PMID 33924978, 2021). "One of the best-known mediators of pruritus is IL-31, which is produced by Th2 cells." (PMID 33923629, 2021). "Moreover, it is thought that IL-31 can induce keratinocytes and infiltrating cells to release additional mediators involved in pruritus." (PMID 34118946, 2021). "Additionally, IL-31 serves as a critical immune-neuron link between Th2 cells and sensory nerves in T cell-mediated pruritus development." (PMID 33923629, 2021). "Twenty-seven dogs were treated with either oclacitinib, a Janus Kinase (JAK) inhibitor that primarily targets JAK1-dependent signaling pathways (n = 17), or lokivetmab, a caninized monoclonal antibody that targets interleukin-31, a cytokine that induces pruritus in dogs (n = 10)." (PMID 34677385, 2021). "According to our study, CD45RO+CLA+H4R+ T cells are an important source of IL-31 in AD, and may be a target for treatment of IL-31-induced pruritus." (PMID 34064490, 2021).
Pruritus (continued). "In autoimmune skin diseases, such as bullous pemphigoid and chronic urticaria, IL-31 may be involved in both pruritus and immunomodulation, potentially underpinning the IgE-associated pathophysiology involved in these diseases." (PMID 33644103, 2021). "In sum, type-2 immune responses and key-cytokines (IL-2, IL-4, IL-13, IL-31) are critically involved in the chronic phase of pruritus pathophysiology, mediating peripheral sensitization mechanisms and abnormal neuro–immune–epithelial cross-talk in several pruritic conditions." (PMID 33807098, 2021). "To note, eosinophils are a source of IL-31, a cytokine that bridges inflammation and pruritus." (PMID 34097126, 2021). "Although the underlying mechanism of pruritus development in AD is not fully understood, recent studies have demonstrated that excessive development of cutaneous sensory nerves and production of sensory nerve stimulants, such as interleukin-31 (IL-31), are involved in the development of pruritus." (PMID 33539470, 2021). "Interleukin 31 has also been demonstrated to be involved in the pathogenesis of chronic skin inflammation and pruritus in patients with chronic spontaneous urticaria, atopic dermatitis, prurigo nodularis, primary cutaneous lymphomas and myeloproliferative disorders including mastocytosis." (PMID 33401724, 2021). "The efficacy of anti-IL-31 treatment against pruritus was first proven in atopic dermatitis." (PMID 33924978, 2021). "There was a low correlation between serum IL-31 concentration and pruritus in the whole patients." (PMID 34118946, 2021). "Recent findings with IL31RA antigen therapy showed a reduction of pruritus in AD patients, indicating that IL31 might be of similarly therapeutic interest in CTCL patients." (PMID 34027133, 2021). "In addition to mediating the sensation of pruritus, IL-31 promotes nerve fiber elongation and the branching of murine small-diameter DRG neurons, which is abrogated in DRG neurons from Il31ra-deficient mice." (PMID 33924978, 2021). "IL-31 signaling in skin keratinocytes also dysregulates filaggrin expression and epidermal differentiation contributing to skin barrier dysfunction in AD, consequently leading to pruritus." (PMID 34276687, 2021). "A subset of affected patients experience severe pruritus but IL-31 signaling in autoimmune inflammation may also facilitate fibrosis and amplify inflammatory circuits." (PMID 33644104, 2021). "As IL-13/IL-4 activate JAK1–STAT6, JAK1 inhibitor reduces pruritus mediated by IL-31 or IL-13/IL-4." (PMID 33233866, 2020). "Furthermore, serum IL-31 levels were significantly reduced after narrowband ultraviolet B (UVB) phototherapy resulting in a substantial reduction in psoriatic patients with pruritus." (PMID 33182442, 2020). "IL-31 plays a major role in development of pruritus, and its signaling engages JAK/STAT pathway." (PMID 32343720, 2020). "Notably, the administration of IL-31 evokes scratching behavior in mouse, dog, and monkey, as well as pruritus in human." (PMID 33233866, 2020). "Thirdly, the influx and polarization of immune cells results in secretion of pro-inflammatory cytokines that activate DRG cells directly; for example, IL-31 from TH2 cells may act on sensory neurons in the generation of T cell-mediated itch in AD." (PMID 32903402, 2020). "The mechanism behind this is still not fully understood, but it has been shown that IL-31RA is expressed on sensory neurons and IL-31 derived from activated T cells under Th2-skewed conditions stimulates IL-31RA on sensory nerves, resulting in severe pruritus in AD." (PMID 31434203, 2019). "Therefore, IL-31/IL-31RA interaction is deeply involved in AD disease activity in addition to pruritus." (PMID 31434203, 2019). "However, since pruritus is also a major feature in bullous pemphigoid, chronic spontaneous urticaria (CsU) and other autoimmune diseases there is a potential role for IL-31 in some of these diseases too." (PMID 31281316, 2019).